SOX2 (SRY-box transcription factor 2)
Diseases named in the same sentence as SOX2 in open-access papers (continued):
Sharing a sentence is not in itself a finding about the gene and the disease.
melanoma (continued). "Further functional studies revealed that depletion of SOX2 heightened the sensitivity of melanoma cells to BRAFi, while overexpression of a phosphomimetic SOX2-S251E mutant (mimicking constant phosphorylation at Ser251) was sufficient to drive resistance." (PMID 40872623, 2025). "This phosphorylation enhances SOX2’s stability, its localization to the nucleus, and its transcriptional activity, contributing to the survival of melanoma cells under BRAFi treatment." (PMID 40872623, 2025). "This overexpression desensitized melanoma cells to treatment both in vitro and in a zebrafish xenograft model, reinforcing the role of SOX2 in mediating resistance." (PMID 40872623, 2025). "Alongside Sox2, JAK (up in the CD24+CD271+ and CD24+CD271− sub-populations) has been associated with melanoma immunotherapy resistance." (PMID 40754577, 2025). "SRY-box2(SOX2) is an embryonic stem cell-expressed gene that keeps melanoma-initiating cells self-renewing and tumorigenic." (PMID 39944829, 2025). "In a nutshell, our results demonstrate that DHT targets STAT3 and suppresses the STAT3/SOX2 signaling pathway to reduce the activity of BRAF mutant melanoma cells." (PMID 39944829, 2025). "Supporting this, soft 3D fibrin matrices were found to increase H3K9 demethylation and Sox2 expression and the self-renewal of melanoma stem cells, while stiff matrices had adverse impacts." (PMID 40277910, 2025). "The investigation revealed that SUZ12, SOX2, TCF3, NANOG and SMAD4 are the maximum chief TFs that control the largest number of genes associated with metastatic-melanoma." (PMID 39820173, 2025). "In melanoma, SOX2 mediates the upregulation of CD24, which promotes the adaptability and resistance of melanoma cells to B-Raf proto-oncogene (BRAF) inhibitor targeted therapy." (PMID 40486886, 2025). "MYC amplification and PTEN loss were mostly prevalent in breast tumors, while amplifications for SOX2 were mostly observed in melanoma." (PMID 38398121, 2024). "SOX2 is important to neural crest development but in melanoma it is a contributor to stemness and invasive ability." (PMID 38426087, 2024). "A positive correlation between the level of SOX2 and the ability of melanoma cells to invade and acquire resistance to treatment is well known." (PMID 39175042, 2024). "Using an in vitro tumor sphere formation assay, we found that DHCR24 contributed to the proliferation of stem-like melanoma cell populations, and the stem cell property of the spheroids was confirmed by the expression of Sox2, CD133, Nanog and ABCB5." (PMID 38775844, 2024). "In a conclusion, we first proposed STAT3 signaling activation by MAPKi, upregulated CSCs markers Oct4 and Sox2 as a mechanism of MAPKi-resistance in melanoma." (PMID 38822350, 2024). "Embryonic stem cell markers, such as Sox2, Oct4 and Notch, have also been shown to be overexpressed in melanoma CSCs." (PMID 39199632, 2024). "Study also showed that activation of HER3/STAT3/SOX2 pathway was the mechanism of resistance against MAPKi in BRAF mutant melanoma cells." (PMID 38822350, 2024). "Intriguingly, SOX2 knockout melanoma cells using the CRISPR/Cas9 system also displayed similar tumor growth patterns compared to the control in xenotransplantation experiments." (PMID 38334608, 2024). "Sox2, another very well-known marker of melanoma stemness, has also been described as a player in the mechanisms of immune resistance." (PMID 39199632, 2024). "Our data was consistent with previous studies, and we confirmed that MAPKi activates STAT3 signaling, upregulating the reprogramming factors Oct4 and Sox2 to resist MAPKi in melanomas." (PMID 38822350, 2024). "Another recent report also finds SOX2 contributes to enhanced oxidative phosphorylation in melanoma." (PMID 38426087, 2024). "Sox2 has been reported to positively regulate the self-renewal of cells in melanoma spheroids as well as of ALDH+ melanoma cells." (PMID 39199632, 2024).
melanoma (continued). "In melanoma, modulation of SOX2 expression was demonstrated to be crucial for the existence of side-population cells and to induce ABCC1 expression that conferred resistance to paclitaxel." (PMID 37176108, 2023). "For example, CAGE promoted stem cell-like properties by upregulating the expression of stemness gene such as SOX2 in melanoma cells." (PMID 37735252, 2023). "This is in line with our data demonstrating that BRAFi induces a SOX2-dependent increase in melanoma cell self-renewal, which is completely abrogated upon SOX2 silencing." (PMID 35944584, 2022). "In comparison, the SOX10+MITF– NCSC-like melanoma cell lines had acquired expression of other NC-derived lineage markers such as SOX2 (expressed in glial lineages), SOX5, and SOX8 (expressed in neural progenitors)." (PMID 36040798, 2022). "Treatment of melanoma cells with increasing doses of both inhibitors for 12 h led to a strong upregulation of SOX2 at both mRNA and protein levels, in line with previous reports." (PMID 35944584, 2022). "SOX2 gene expression in RB tissues increases with progression of clinical stage, while the role of SOX2 in melanoma is controversial." (PMID 36012688, 2022). "Supporting the results from the melanoma cell lines, we found increased expression of SOX9 and loss of expression of SOX2, SOX5, and SOX8, suggesting that SOX10KO cells reverted to a pre-NC state." (PMID 36040798, 2022). "Melanoma CSCs are mainly characterized by upregulated levels of surface stem factors, including Nanog, Sox2, and Oct4, and their sphere formation capacity in vitro and in vivo." (PMID 35761835, 2022). "Since our models are derived from a BRAFV600E PTEN-null melanoma, we first evaluated changes in PI3K/Akt and MAPK signaling associated FMOD and/or SOX2 loss." (PMID 35737114, 2022). "In this study, we identify p38 MAPK as a novel mediator of the adaptive response to BRAFi in melanoma and uncover a putative p38 phosphorylation site that enhances SOX2 stability and transactivation activity." (PMID 35944584, 2022). "In fact, Sox2 contributes to melanoma cell invasion and is a critical factor for self-renewal and tumorigenicity of melanoma-initiating cells." (PMID 36325671, 2022). "In this study, we observed significant downregulation of Sox2 expression in melanoma CSCs and the expression of two other stem factors, Nanog and Oct4, which are critical for maintaining stemness." (PMID 35761835, 2022). "Several studies have shown that SOX2 plays a critical role in promoting a cancer-stem like phenotype in multiple tumors, including melanoma." (PMID 35944584, 2022). "We then transfected melanoma cells with SOX2-WT and evaluated SOX2 phosphorylation level upon PLX4032 in presence or absence of p38 with a Ser251 phospho-specific antibody." (PMID 35944584, 2022). "Recent studies uncovered that SOX2 triggered resistant to T cell‐mediated cytotoxicity and anti‐PD‐1 with PD‐L1 high expression in melanoma." (PMID 35415876, 2022). "An agent that downregulates both pRB and SOX2 would be expected to have potent activity against melanoma." (PMID 35624662, 2022). "We then conducted a MDR efflux assay and found that SOX2 silencing strongly counteracted the efflux activity of BCRP/ABCG2 transporter induced by PLX4032 in all BRAFV600E melanoma cells tested." (PMID 35944584, 2022). "Tumorigenic potential and tumor-initiating capacity are significantly increased in melanoma cells with CDK1 overexpression due to its interaction with the pluripotent stem cell transcription factor Sox2." (PMID 35681641, 2022). "In melanoma, Hh signaling increased SOX2 expression and thereby supported self-renewal and tumorigenicity, whereas SOX2 silencing or depletion blocked cell growth, sphere formation, and the ability to initiate tumors in xenograft models." (PMID 36118530, 2022). "On the other hand, SOX2 was thought to be a prognostic marker for patients with breast, colorectal, gastric cancer, and melanoma." (PMID 35055392, 2022).
melanoma (continued). "A study showed that treatment of melanoma cells with BRAFi induces STAT3-dependent expression of SOX2, which, together with CD24, contributes to create an autoregulatory loop that sustains adaptive resistance to BRAF-targeted therapy." (PMID 35944584, 2022). "The highest expression of YY1 and Sox2 proteins represented the group assembled by melanoma, colorectal cancer, and lymphomas." (PMID 35719931, 2022). "In this study, we also provide evidence that SOX2 desensitizes melanoma cells to BRAF inhibition, likely by decreasing intracellular drug accumulation through transcriptional activation of the ABCG2/BCRP drug efflux transporter." (PMID 35944584, 2022). "We also examined expression levels of Usp9x and SOX2 in fresh tumor tissue from melanoma patients primary or metastatic sites." (PMID 33613844, 2021). "We also show that protein levels of TF SOX2 were induced dose dependent in mutant BRAF melanoma cell lines, A375, treated with BRAFi, vemurafenib, and MEKi, PD0325901." (PMID 33613844, 2021). "In support of this notion, two prior studies showed that Gli1 induces SOX2 expression in melanoma and pancreatic cancer through a cis-element in the SOX2 promoter." (PMID 33499351, 2021). "One study found that higher levels of SOX2 in melanoma have been correlated with increased primary tumor thickness and invasiveness." (PMID 34831420, 2021). "Dose response of a panel of melanoma cell lines to G9, showed that BRAF mutant melanoma cells were sensitive to G9, and the degree of sensitivity correlated with Usp9x and SOX2 expression." (PMID 33613844, 2021). "We confirm that protein levels of TF SOX2 were induced in mutant BRAF melanoma cell lines, A375 (top) and SK-Mel28 (middle), treated with BRAFi, vemurafenib, and MEKi, PD0325901." (PMID 33613844, 2021). "In conclusion, our work provides a rationale for the development of a Usp9x inhibitor (small molecule) for overcoming resistance to treatment by MAPK/ERK inhibitors via depletion of SOX2 in melanoma and other tumors including prostate." (PMID 33613844, 2021). "SOX2 contributes to metabolic plasticity and a shift towards an oxidative metabolism in melanoma cells through multiple mechanisms." (PMID 34831420, 2021). "A recent study showed that in melanoma cells the oncogenic TFs SOX2 and GLI1 co-regulate ST3GAL1 transcription." (PMID 33921986, 2021). "Consistently, we find a positive correlation between the expression of GLI1 and SOX2 in human melanoma samples and cell lines." (PMID 33958721, 2021). "Other studies have shown that SOX2 plays a significant role in melanoma progression and cell invasion." (PMID 33613844, 2021). "Usp9x inhibition provides an avenue for new treatment options for patients with melanoma who either have endogenously high SOX2 or can induce SOX2 upon treatment with kinase inhibitors, especially as a combination with other therapies." (PMID 33613844, 2021). "Here we show that Usp9x plays a key role in SOX2 regulation and in melanoma tumorigenicity, particularly in tumors driven by BRAF mutation and dependent on SOX2." (PMID 33613844, 2021). "We identified SOX2 as a substrate of Usp9x in melanoma and determined that SOX2 escapes proteasomal destruction by Usp9x-mediated deubiquitination." (PMID 33613844, 2021). "In skin, SOX2 is expressed in cutaneous neuroendocrine carcinoma (Merkel cell carcinoma) in addition to other subsets of melanoma." (PMID 33613844, 2021). "Usp9x KD blocked the induction of SOX2 by vemurafenib or MEKi treatment in melanoma cell lines with mutant BRAF, A375, SK-Mel28 and wild type BRAF, SK-Mel147." (PMID 33613844, 2021). "For instance, the knockdown of SOX2 expression in A2058 melanoma cells led to a 4.5-fold decrease in invasiveness, while the overexpression of SOX2 in G361 cells via transduction was associated with a 3.8-fold increase in invasiveness in vitro." (PMID 34831420, 2021).
melanoma (continued). "To further assess regulation of SOX2 by deubiquitination in melanoma, we examined the activity of our recently described DUB inhibitor, G9." (PMID 33613844, 2021). "Pharmacological inhibition of BRAF with vemurafenib and MEK with PD0325901 markedly reduced basal phospho-ERK (pERK) in melanoma cells while increasing SOX2, and this induction was specific to the inhibitor treatment as it was time dependent." (PMID 33613844, 2021). "Considered together, our results indicate that SOX2 is a polyubiquitinated protein with an unexpectedly high turnover rate in melanoma cells which can be controlled by the deubiquitinase Usp9X." (PMID 33613844, 2021). "Usp9x knockdown in melanoma increased SOX2 ubiquitination, leading to its depletion, and enhanced apoptotic effects of BRAF inhibitor and MEK inhibitors." (PMID 33613844, 2021). "Despite observations on the metabolic effects of SOX2 activation, the role of SOX2 in the initiation and progression of melanoma is somewhat unclear, as different studies yielded different conclusions regarding SOX2." (PMID 34831420, 2021). "Positive controls showed transcript expression for OCT4 on seminoma, SOX2 on melanoma, KLF4 on sweat glands, and c-MYC on normal colon." (PMID 33816543, 2021). "Other evidence showed that SOX2 knockdown in A2058 melanoma cells led to similar growth patterns to control cells in vitro, but SOX2 knockdown in vivo resulted in decreased tumor growth." (PMID 34831420, 2021). "We noticed that proteasome inhibitors MG132 and bortezomib can transiently increase SOX2 levels in melanoma cells, suggesting proteasomal degradation of SOX2." (PMID 33613844, 2021). "To further assess long-term consequences of Usp9x and SOX2 inhibition, we analyzed the ability of melanoma cells to form colonies in 3-dimensional (3D) growth conditions in matrigel that more closely recapitulates tumor growth in vivo." (PMID 33613844, 2021). "Combined BRAF (vemurafenib) and DUB inhibition effectively suppressed BRAF mutant melanoma in vitro colony growth (2D and 3D) and in vivo tumor growth, suggesting that combining these agents can block adaptive resistance mechanisms such as SOX2 induction." (PMID 33613844, 2021). "Correlation of expression of SOX2 and Usp9x is evident in cell line models so we next interrogated this in human primary melanoma cells and metastatic tumors." (PMID 33613844, 2021). "We also provided a rationale to explore a novel combination of ICIs with SAHA clinically, especially in melanoma with PD-L1 and SOX2 high expression." (PMID 33158915, 2020). "Our results showed that both GLI1 and SOX2 increased melanoma cell invasion and that depletion of ST3GAL1 was able to suppress the effects of both SOX2 and GLI1." (PMID 33203881, 2020). "Taken together, our study reveals a functional SOX2/GLI1-ST3GAL1-AXL axis in a subgroup of melanomas involved in cancer progression, and highlights the therapeutic potential of targeting ST3GAL1 to prevent or treat metastatic melanoma." (PMID 33203881, 2020). "Through Hedgehog-GLI signaling, GLI regulates the SOX2 gene, and GLI-mediated regulation of SOX2 induces self-renewal of melanoma and lung CSCs." (PMID 32033067, 2020). "Collectively, we identified SOX2 as a biomarker for identifying melanoma patients who will response to the combination therapies of SAHA and ICIs, while its predictive value of response or survival warrants further investigation in prospective clinical trials." (PMID 33158915, 2020). "It has been demonstrated that SOX2 as a part of STAT3-SOX2-CD24 axis rescued melanoma cells against acute exposure to vemurafenib." (PMID 31936151, 2020). "The silencing of SOX2 gene shifts the metabolism of acidic melanoma cells toward glycolysis, thus making cancer cells less vulnerable to metformin treatment." (PMID 32528879, 2020). "Consistently, ectopic expression of ST3GAL1 in SOX2- or GLI1-depleted SSM2c cells was able to rescue the decrease in melanoma cell invasion produced by SOX2 or GLI1 silencing." (PMID 33203881, 2020).
melanoma (continued). "Here we show that the sialyltransferase ST3GAL1 is transcriptionally regulated by both GLI1 and SOX2 in melanoma and is a crucial driver of melanoma cell invasiveness and melanoma metastasis in vivo." (PMID 33203881, 2020). "We then analyzed NGFR and SOX2 protein levels in both adherent and sphere melanoma cells by western blot (WB) analysis, as both of the proteins have been used as markers for MICs15,27." (PMID 32686661, 2020). "To confirm that knockdown of CACNA1H was responsible for changes in differentiation status, we measured SOX2 expression in human melanoma cells." (PMID 32063604, 2020). "Expression of canonical melanoma stem cell marker proteins (SOX2, OCT4, KI67) was also similar between the cell preparations, strongly suggesting the NME1LOW subpopulation does not possess increased stemness relative to the parent population." (PMID 32029850, 2020). "The elevated STAT3 expression causes an increase in the expression of SRY-Box Transcription Factor 2 (SOX2), which is an important factor in melanoma cell resistance." (PMID 33327495, 2020). "We found that SOX2 was an independent predictor for poor survival and resistance to anti-PD-1 therapy in melanoma with high PD-L1 expression." (PMID 33158915, 2020). "Potentially, CD24 expression was mediated by STAT3-dependent /SOX2-mediated pathways that was correlated with adaptive resistance toward targeted therapy in melanoma." (PMID 33196458, 2020). "Overall, these data reveal ST3GAL1 as a key downstream mediator that contributes to the aggressive behavior of melanoma cells induced by SOX2 and GLI1." (PMID 33203881, 2020). "We generated SOX2 KD melanoma cell lines (ME4405 and MM200) by indicated shRNA and performed a T-cell-mediated cytotoxicity assays." (PMID 33158915, 2020). "For example, YY1 inhibits proliferation in pancreatic cancer through downregulation of SOX2, while in melanoma, YY1 promotes tumor growth, and YY1 cKO prevents tumorigenesis in a melanoma murine model." (PMID 33102493, 2020). "Western blots showed that primary melanoma cells express lower levels of SOX2, GLI1, ST3GAL1, and AXL than metastatic melanoma cells, and that the latters harbor a stronger activation of SOX2/GLI1-ST3GAL1-AXL axis." (PMID 33203881, 2020). "Sox2 is highly expressed in melanoma stem cells contributing to dermal invasion and primary tumor thickness." (PMID 32899370, 2020). "As several reports suggest genetic context-dependent role of SOX2 in melanoma, regulation of SOX2 expression and the role of this transcription factor in resistant melanoma cells remain to be clarified." (PMID 31936151, 2020). "Since GLI1-mediated regulation of SOX2 regulates the self-renewal of lung and melanoma CSCs, we examined SOX2 levels using ciclesonide." (PMID 32033067, 2020). "Analyzing the expression of known STAT3 target genes in different melanoma cell lines upon vem treatment, we found a significant reduction of the expression levels of most genes; in contrast, SOX2 expression was significantly upregulated." (PMID 33327495, 2020). "Acidic melanoma cells over-express SOX2, which is crucial for the maintenance of their oxidative metabolism, and carbonic anhydrase IX, that correlates with poor prognosis of cancer patients." (PMID 32803272, 2020). "For example, CDK1 was reported to interact with Sox2 and promote tumor initiation in human melanoma, CCNA2 and AURKA inhibitors are now available and has shown encouraging effect for treatment of melanoma." (PMID 31921860, 2019). "Whereas some reports, including ours, revealed the importance of SOX2 in tumor initiation, others demonstrated an opposite trend using mouse melanoma models." (PMID 31080551, 2019). "Strikingly, we found little off-target expression of SOX2 (neuronal precursor cells) or PMEL (melanoma cells) in D32 transplanted organoids compared to controls, suggesting that transplantation diminished off-target cells." (PMID 31784515, 2019).